RNU7-115P (RNA, U7 small nuclear 115 pseudogene)
Gene: Small nuclear RNA gene on chromosome 17 (64,825,765 to 64,825,819, reverse strand). Ensembl gene ENSG00000252242.
Homologues: Orthologues: pig U7 (76% identical). Paralogues in human: RNU7-138P (85% identical), RNU7-127P (84% identical), RNU7-167P (84% identical), RNU7-19P (84% identical), RNU7-24P (84% identical), RNU7-50P (84% identical), RNU7-70P (84% identical), RNU7-1 (82% identical), RNU7-107P (82% identical), RNU7-187P (82% identical), RNU7-34P (82% identical), RNU7-7P (82% identical), and 142 more.